SNORD113-4 (small nucleolar RNA, C/D box 113-4)
Synonyms: 14q(I-4)
Gene: Small nucleolar RNA gene on chromosome 14 (100,936,491 to 100,936,565, forward strand). Ensembl gene ENSG00000201672.
Gene Ontology:
Biological process: RNA processing
Cellular component: nucleolus
Homologues: Orthologues: chimpanzee SNORD113-4 (100% identical), macaque SNORD113-4 (99% identical), pig SNORD113-4 (89% identical), rabbit SNORD113-4 (80% identical), mouse Gm55109 (67% identical). Paralogues in human: SNORD113-6 (89% identical), SNORD113-8 (79% identical), SNORD113-9 (79% identical), SNORD113-3 (77% identical), SNORD113-5 (73% identical), SNORD113-7 (73% identical), SNORD114-12 (65% identical), SNORD114-2 (64% identical), SNORD114-18 (63% identical), SNORD114-22 (63% identical), SNORD114-3 (63% identical), SNORD114-10 (61% identical), and 26 more.